APC (APC regulator of Wnt signaling pathway)
Diseases named in the same sentence as APC in open-access papers (continued):
Sharing a sentence is not in itself a finding about the gene and the disease.
cancer (continued). "Thus, cancer cells with APC mutations have a diminished capacity to correct erroneous kinetochore-microtubule attachments, which would account for the widespread occurrence of CIN in tumors." (PMID 23734346, 2013). "Mutations of APC were detected in a wide variety of human cancers, including MB." (PMID 23094051, 2012). "We discuss how these missense mutations in the large unstructured region of APC may predispose to cancer." (PMID 21859464, 2011). "These suggest functions in chromosomal segregation and spindle positioning whose loss might contribute to tumourigenesis in cancers initiated by APC mutation." (PMID 22216133, 2011). "However, for some cancers, β-catenin accumulates in the nucleus even though mutation of β-catenin or APC is rare." (PMID 20302655, 2010). "Decades in normal colon can also help explain why pathways to cancer almost always collect an APC mutation that may favor persistence during niche clonal evolution and lessen a fixation requirement for subsequent driver mutations." (PMID 20051132, 2010). "Several of these functions are altered by cancer-associated APC mutations." (PMID 21152425, 2010). "APC mutations may shorten pathways to cancer by effectively increasing the numbers of stem cells at risk." (PMID 20051132, 2010). "However, allelic loss of APC has been shown to increase in frequency as there is progression towards carcinoma." (PMID 19424478, 2008). "In cancer, mutations in the APC gene allow for accumulation of β-catenin." (PMID 16417629, 2006). "To determine whether there is evidence for similar priming events that may impact APC function in human CRC, we obtained genomic data from 17,000 CRCs from the AACR Project GENIE cancer registry and filtered the dataset to include only cancers with two APC-truncating mutations." (PMID 41339549, 2026). "APC-driven predisposition increases cancer initiation, and one mutated allele is sufficient to initiate the tumorigenesis, and this is where altered DNA methylation targeting various growth-related genes may be one of the early mechanisms accelerating the tumorigenic process." (PMID 40753397, 2025). "APC gene, being a well-known characterized tumor suppressor gene, when it comes to hypermethylation, this gene was proven to be associated with different types of cancer, colorectal, breast, etc., and its significative correlation with tumor characteristics and cancer cell formation." (PMID 39569232, 2024). "Given the HT-29′s mutation in the APC gene and the potential upregulation of Wnt signalling, the addition of extract #18 may alter the oncogenic signalling of this pathway, potentially exerting an anti-cancer effect." (PMID 38674023, 2024). "Thus, the APC/C becomes the sole regulator of the G1/S transition in these Rb-deficient cancers." (PMID 38727267, 2024). "Thus, C3 could serve a similar function in APC-related cancers by maintaining the association of metastatic cells in transit." (PMID 37489330, 2023). "The mutation of AXIN2 or APC gene may change the conformation of the binding site of the 2 proteins, resulting in a decreased affinity between the 2 proteins and the occurrence of cancer." (PMID 36042639, 2022). "The second group belongs to nonhypermutated tumors (~84%) that are microsatellite stable (MSS) cancers with a high frequency of DNA somatic copy number alterations (SCNAs) and dysregulated Wnt pathway with frequent mutations in genes including adenomatous polyposis coli (APC) and Kirsten ras (KRAS)." (PMID 33917100, 2021).
cancer (continued). "As a result of inactivation of APC transcription, transcripts expressed from 1A are significantly decreased, therefore it is quite likely that the Wnt signaling pathway may be activated, further causing cancer development in cells with hypermethylated APC." (PMID 33968756, 2021). "Therefore, molecular targeting of the upstream molecules of APC and β-catenin might be promising in Wnt/β-catenin signaling-associated cancer." (PMID 33291655, 2020). "In addition to APC mutations, β-catenin can be further activated by additional layers of regulation, which demonstrated the complexity of Wnt signaling deregulation in cancer." (PMID 32037398, 2020). "Furthermore, the study on mutation hotspot information may be more robust in that the hotspot mutations represent functionally relevant cancer drivers as shown in the example of APC mutations in COADREAD." (PMID 29697365, 2018). "Here we address whether the nuclear supply of β-catenin is also inhibited by E-cadherin, especially in the cancer specific context of loss of function of the APC associated destruction complex, and whether inhibition is extra-cellular adhesion domain dependent." (PMID 27566565, 2016). "Using these innovative approaches with the FAP-hESCs studies here, will enable us to study in vitro, in a human based model, the earliest cellular and molecular events directly caused by the inactivation of APC and how this might lead to cancer initiation in otherwise normal cells." (PMID 28010732, 2016). "However, mutations to APC and β-catenin are rare in this cancer, suggesting that Wnt signalling could be activated at the level of the receptor in cervical cancer." (PMID 27196929, 2016). "In addition to the APC mutation, these already differentiated cells reportedly carry some other mutations that are only partly characterized and thus have limitations in providing necessary data on the initial molecular steps leading to cancer formation." (PMID 28010732, 2016). "Therefore, the cancer-associated hypermethylation of this APC intron/promoter region might help regulate levels of alternate promoter usage for this gene." (PMID 26510686, 2015). "However, it is conceivable that the loss of APC renders these cancers dependent on APC2, and to our knowledge this hypothesis has not been tested." (PMID 24806839, 2014). "Whereas APC plays a role in hereditary nonpolyposis colorectal cancer (HNPCC), and is methylated in the tumorigenesis of other cancers, mutated APC may be of value in predicting secondary malignancies if more data are made available about its status during tumorigenesis of secondary cancers." (PMID 25493073, 2014). "However, the unusual mutation spectrum at FBXW7 in human cancers was reminiscent of the adenomatous polyposis coli (APC) gene, in which cancer-associated mutations are selected for partial retention of protein function 14 so as to provide a “just right” level of Wnt signalling." (PMID 21503901, 2011). "Furthermore, by classification and localization of known cancer-related APC missense mutations, we uncover different mutational spectra of germline and somatic missense mutations along the APC protein sequence, suggesting variation in functional relevance and mechanisms." (PMID 21859464, 2011). "In this study, we further discovered that APC11, beyond its classical role in regulating cell cycle progression via the APC/C complex, also modulates cancer cell migration in vitro and metastasis in vivo." (PMID 41159544, 2026).
cancer (continued). "Cancer cell viability was measured by Resazurin cytotoxicity assay and the gene and protein expression of APC, KRAS, TTN, HIF-1α, HIF-1β, and GLUT-1 were measured using rtPCR and ELISA." (PMID 41797969, 2026). "In BC, piR-823 upregulated DNMTs expression levels, promoted DNA methylation of the adenomatous polyposis coli (APC) gene, activated Wnt signaling, and induced cancer cell stemness in luminal subtype cells." (PMID 41596471, 2026). "Recent research has identified the APC/C and its co-activators as significant contributors to cancer development." (PMID 40136519, 2025). "The adenomatous polyposis coli (APC) gene demonstrates a high mutation rate of up to 60% in CRC, rendering it a crucial molecular target in investigating SL anti-cancer strategies." (PMID 39403687, 2025). "Epigenetic alterations, such as promoter hypermethylation of tumor suppressor genes (e.g., APC, TIMP3, CDH13), can serve as biomarkers to identify patients at higher risk of progression from BE to cancer." (PMID 40149421, 2025). "By integrating somatic and cancer datasets with mathematical modeling, we find a quantitatively consistent signal that biallelic APC genotypes, which retain intermediate β-catenin binding activity, confer maximal tumorigenic effect." (PMID 41091816, 2025). "Intersection analysis of YTHDC2-associated genes with the Catalogue of Cancer Genes (CCG) revealed several cancer-related genes, such as DMXL1, CHD1, and APC, showing strong positive association with YTHDC2 expression." (PMID 41145440, 2025). "The aim of this study is to evaluate the relationship between the methylation and expression of APC, SFRP1, SFRP2, SFRP4, and SFRP5 genes involved in the Wnt signaling pathway and the risk of cancer development in IBD." (PMID 40521787, 2025). "SBS88 accounted for 64.3% of the colibactin-induced42APC splicing variant c.835-8A>G in colibactin-exposed samples, compared with only 3.9% and 3.8% of driver substitutions in APC or other cancer genes." (PMID 40267983, 2025). "Analysis of sequence data from >2,500 colorectal cancers showed that APC genotypes resulting in partial protein function confer about 50 times higher probability of progressing to cancer compared with complete APC inactivation." (PMID 41091816, 2025). "WNT signaling orchestrates key developmental and homeostatic events; however, its aberrant activation, often driven by mutations in APC, CTNNB1, or AXIN, significantly contributes to the development of cancer." (PMID 40874062, 2025). "Spontaneous formation of intestinal tumors in these APC‐mutant mice closely resembles key metabolic, inflammatory, and physiological aspects of human cancers." (PMID 40985218, 2025). "Expanding on our FAP-hESC colon organoid model and Rapamycin’s success in preventing APC mutant mouse cancer, we investigate its potential to reverse cancer-like features in our in vitro human model." (PMID 40702333, 2025). "Mutation of APC, AXIN1/2 or β-catenin itself, results in the formation of cancers with aberrantly increased β-catenin signaling, which have become largely independent of extracellular Wnt ligands." (PMID 39674817, 2025). "A method was developed to detect the cancer-specific C-terminal deletion mutant of the APC protein (dAPC) using an Alexa488-labeled anti-APC antibody for the N-terminal and an Alexa647-labeled anti-APC antibody for the C-terminal." (PMID 39858085, 2025).
cancer (continued). "Collectively, our findings establish OncoLRC as a simple yet effective APC-targeted mRNA delivery platform, highlighting its potential as a next-generation mRNA cancer vaccine system." (PMID 41271591, 2025). "In CRC, mutations in APC that involve the CTBP–APC interaction lead to a dysfunctional Wnt signaling, driving cancer development." (PMID 40362431, 2025). "Cancer vaccines can be classified into cell-based, peptide-based, nucleic acid-based, and viral vector-based types, depending on the method of APC activation." (PMID 40429703, 2025). "After the mAb selectively binds to the antigens on the surface of the cancer cells, NIR irradiation will lead to photochemical reactions of the APC, which will trigger the rupture of the membrane and cause cell death." (PMID 40574027, 2025). "APC mutations are the most frequently observed mutations, and KRAS mutations are considered major cancer-related genetic mutations." (PMID 41488735, 2025). "In conclusion, this study highlights the potential of targeting shared frameshift neoantigens, particularly those derived from the APC gene, for cancer immunotherapy." (PMID 40443655, 2025). "Germline variants in MUTYH are associated with a distinctive mutational signature in CRC, characterized by an excess of G:C>T:A transversions, particularly affecting cancer driver genes such as APC and KRAS." (PMID 41001951, 2025). "These engineered T cells specifically recognized target cells presenting these neoantigens and cytotoxic activity against them, supporting the therapeutic potential of targeting APC frameshift neoantigens in cancer immunotherapy." (PMID 40443655, 2025). "The WNT/APC/β-catenin pathway is a prominent cancer-related signaling pathway deregulated in gastrointestinal cancers and a regulator of CDX2 expression." (PMID 40149431, 2025). "To test and quantify the effect of different APC inactivation levels for cancer initiation, we applied our mathematical model to the 100kGP cohort." (PMID 41091816, 2025). "ZNRF3-mutant CRCs carrying additional APC truncations or oncogenic CTNNB1 mutations classically linked to β-catenin activation, are only observed in 5 and 1 cancer, respectively." (PMID 39674817, 2025). "The molecular contribution of CIMP-H and BRAF-mutant to APC mutant-free cancer initiation of serrated type CRC has been widely discussed." (PMID 40357363, 2025). "Mutations in the APC gene have been linked to an elevated risk of colorectal cancer (CRC), as well as other cancers such as gastric and pancreatic malignancies." (PMID 40657252, 2025). "Among the 13 patients harboring a MUTYH variant there were 3 patients carrying a VUS and/or a novel variant in other cancer susceptibility genes, in particular we found one VUS: the VUS in APC, c.7610C>G (P.Ser2537Cys), seen in patient 9, and 5 novel variants." (PMID 41001951, 2025). "APC promoter methylation appears to be an ideal cancer biomarker, as a previous study showed it to be an early event in various malignancies." (PMID 40149421, 2025).
cancer (continued). "Data were curated from peer-reviewed articles, grounded in mechanistic studies using cell lines (SW480, MCF7 (Michigan cancer foundation-7)) and animal models (APC-mutant mice), with a focus on mechanistic studies, omics analyses, and translational research." (PMID 40786181, 2025). "Because human ERKs are homologs of fission yeast Pmk1, the finding in this study supports a notion that very likely human MAPKs also negatively regulates APC/C through Cdc20 phosphorylation and the altered levels of Cdc20 in cancers are MAPK relevant." (PMID 39412391, 2024). "Silencing of APC in cancer cell lines resulted in perinuclear accumulation of mitochondria and reduced the number of motile mitochondria." (PMID 38607086, 2024). "Carcinogenesis in the large intestine can lead to the loss of tumor suppressor genes, such as APC and SMAD4, which normally prevent cancer development." (PMID 38674816, 2024). "In primary MSI cancers, frequencies of BRAF and RNF43 mutations were lower in younger patients, with correspondingly higher APC frequency (P < 0.05, two-sided Wilcoxon test)." (PMID 39112709, 2024). "In contrast, genes such as APC, KRAS, CTNNB1, and GATA6, showed a higher mutation frequency in precancerous lesions than in advanced cancer." (PMID 39554798, 2024). "This is consistent with several studies suggesting that signaling networks, such as the APC/Wnt/β-catenin pathway, are crucial in cancer, corroborated by our findings on genetic changes occurring in PH." (PMID 39635438, 2024). "Phosphorylation of its co-activator CDH1 modulates the E3 ligase activity, but little is known about its regulation after phosphorylation and how to effectively harness APC/CCDH1 activity to treat cancer." (PMID 38622115, 2024). "We hope that this work motivates future study to mechanistically characterize how APC shapes poly(A) site selection in cancer as well as functional study of specific APA events that contribute to tumorigenesis." (PMID 39375704, 2024). "The significance in mutational status of APC and PIK3CA between the two different cancer types is dominated by male patients with sCRC." (PMID 39390564, 2024). "Taken together, the data suggest that APC-dependent actin nucleation is required for robust cancer cell invasiveness." (PMID 38680662, 2024). "Nevertheless, inhibition of APC/CCdc20 activity or induction of Cdc20 degradation have already been listed as alternative therapeutic strategies to control cancer." (PMID 39412391, 2024). "In particular, genetic testing revealed that four of these patients (families 15, 16, 19, and 20) who had a personal and family history of CPs and cancer harbored four different germline VUSs involving adenomatous polyposis genes (APC and MUTYH)." (PMID 39518056, 2024). "A better appreciation of the role of the APC/C in generating KIF18Ai sensitivity raises the question of why cancer cells would select for APC/C dysfunction." (PMID 38279026, 2024).